CD38 (CD38 molecule)
Diseases named in the same sentence as CD38 in open-access papers (continued):
Sharing a sentence is not in itself a finding about the gene and the disease.
cancer (continued). "Given that CD38 is intimately linked with cancer metabolism, we considered the possibility that CD38 activity might induce adaptation of cellular metabolism, which in turn modulate the expression of CD38." (PMID 38545257, 2024). "High mobility group box 1 protein (HMGB1) present in exosomes derived from hepatocarcinoma cells induces a population of IL-10-secreting TIM-1+Bregs (CD5highCD24-CD27−/+CD38+/high) which is associated with advanced stages of cancer development and reduced patient survival." (PMID 35350071, 2022). "The function of CD38 in myeloid cells warrants further study, and this marker may be utilized in routine diagnostic work in the era of cancer immunotherapy." (PMID 31552039, 2019). "Therefore, for the first time, to our knowledge, we revealed the status of cellular differentiation and CD38 expression can change the ability of cancer cells to acquire resistant genetic mutations to a therapeutic agent." (PMID 24967705, 2014). "Importantly, these studies underscore the necessity to better resolve the impact of CD38 deficiency on brain metabolism, considering ongoing clinical trials and discussions related to the use of CD38 modulators for the treatment of cancers, age‐related decline, and neurodegenerative disease." (PMID 41400119, 2026). "This elevated CD38 expression has been associated with poorer prognosis and a more aggressive cancer phenotype, which is an outcome of the cancer cell hijacking underlying CD38-driven functions to create both a pro-tumoral extracellular environment and a cancer-permissive intracellular milieu." (PMID 36139103, 2022). "The effect of a unit of control on the mortality rate of CD38+ cancer cells, μPu, is fixed at one; this defines the scale for the control u." (PMID 40788967, 2025). "In recent years, great interest has been shown in the study of CD38 in aging and age-related diseases, including cancer, metabolic diseases, and neurodegenerative diseases." (PMID 40529366, 2025). "CD38 and HLA-DR are cell surface markers that play important roles in immune response and cancer biology." (PMID 39941799, 2025). "During the break in treatment the healthy cell population recovers while the drug resistant CD38- population declines, but the CD38+ cancer subpopulation also recovers from low levels." (PMID 40788967, 2025). "The drug resistance mechanism requires that cancer cell CD38 expression can vary, and the Darwinian selection mechanism requires natural variation in the population." (PMID 40788967, 2025). "Previous work has shown the existence of CD38+ MDSC populations in cancer, and others have found that cancer cells can overexpress CD38 on their cell surface following development of acquired resistance to PD-1/PD-L1 blockade." (PMID 40327401, 2025). "Higher CD38 expression enhances MDSCs’ ability to suppress T cell activation and promote cancer progression." (PMID 40136652, 2025). "Researchers have postulated that the resistance to anti-PD-1/PD-L1 immunotherapy in cancer cells is orchestrated by CD38-mediated-ADO production, a process known as CD38-ADO-mediated immune suppression." (PMID 39805878, 2025). "The model incorporates proposed mechanisms by which the cancer resists Daratumumab by reduced expression of the receptor CD38, which is the drug target and normally abundant in the cancer cells." (PMID 40788967, 2025). "In fact, the solutions with δP=δN=0 appear to suggest that permanent control of the CD38+ cancer has been achieved, which is inconsistent with α=0; there is also an untreatable CD38- cancer population when δPu>0." (PMID 40788967, 2025). "Our model extends the core features of the Sharp model, which we reproduce as the Null-N model by taking our full model and suppressing the drug resistant CD38- cancer cell population (N) and the off-target drug effect." (PMID 40788967, 2025).
cancer (continued). "Our previous studies demonstrated that macrophage co-cultivation with 4T1 cancer cell spheroids leads to the upregulation of CD38 and IFNβ in macrophages." (PMID 40547518, 2025). "Of note, we found CD38 to be mostly expressed by endothelial cells, whereas previous work found T cell and cancer cell expression to be informative." (PMID 39975273, 2025). "CD38 contributes to immune evasion by recruiting suppressive immune cells, thereby participating in cancer progression." (PMID 40677211, 2025). "To determine activation status of total T cells and SARS-CoV-2 tetramer-specific T cells, we assessed activation markers CD38, HLA-DR, and proliferative marker CD71, as well as TIM-3 and PD-1, linked to T cell exhaustion in chronic diseases and cancers." (PMID 39284068, 2024). "In these tumors, CD38 not only regulates cancer cell survival and proliferation through metabolic pathways but is also linked to immune evasion mechanisms." (PMID 39852780, 2024). "As a result, considerable efforts are being pursued to inhibit extracellular NAD+ signaling in cancer by targeting CD38, thereby enhancing immune response." (PMID 38399441, 2024). "On the other hand, CD38-targeting mAbs, in combination with IMiD, have demonstrated profound anti-cancer activity with manageable safety profiles in relapsed/refractory and newly diagnosed MM patients." (PMID 38765013, 2024). "Across all types of CD38 expressing cancers, [68Ga]Ga‐AJ206 provides an opportunity to identify new imaging biomarkers for disease prognosis." (PMID 38421139, 2024). "These evidences emphasized the role of CD38 in malignant tumors and underscored its significance as a target in cancer immunotherapy." (PMID 38463232, 2024). "Since amino acid metabolism, especially methionine metabolism, is crucial for cancer stem cells to survive, we tested the effect of 8CA/8AA on Lin−CD45dimCD34+CD38- LSCs." (PMID 38643304, 2024). "CD38 shows especially high and uniform expression on MM cells, in which it plays a relevant role in cancer cell pathology, making it a target of choice for therapeutic antibodies targeting cell surface molecules in MM." (PMID 37760502, 2023). "Compared to cancer patients who received therapies other than anti-PD-1 antibodies or healthy control individuals, patients with cancer receiving anti-PD-1 antibodies exhibited a 2.6-fold expansion of ICOS+CD38+ Tfh cells on average one week after vaccination." (PMID 36380097, 2023). "The mechanisms underpinning how anti-CD38 therapy influences normal PCs or PC differentiation beyond cancer settings have remained virtually unexplored." (PMID 37419630, 2023). "Extracellular vesicle (EV)-mediated transfer of CD38 siRNA (EVs/siCD38) facilitated macrophage repolarization toward M1-like phenotype and phagocytosis of cancer cells by macrophages through inhibition of CD38-mediated adenosine generation." (PMID 37767098, 2023). "To take advantage of the unique properties of IgE antibodies as cancer therapeutics and to address unmet medical needs in MM, we now report, for the first time, the development of a new fully human anti-CD38 IgE as a potential targeted immunotherapy for MM." (PMID 37760502, 2023). "CD38 has also been identified as a cell surface marker in hematologic cancers such as MM, but the effects of CD38 on different immune cells and other cancers are still being explored." (PMID 37834375, 2023). "In pan-human cancers, a high cytotoxic CD38+CD39+CD4+ T-cell gene signature correlates with better clinical prognosis." (PMID 36869048, 2023). "The first key gene, CD38, is the major NAD-hydrolyzing ectoenzyme in most mammals and has recently been implicated in regulating metabolism and the pathogenesis of cancers." (PMID 36845744, 2023). "WT-161 is a potent histone deacetylase 6 (HDAC6) inhibitor widely used in cancer treatment by targeting the expression of CD38." (PMID 36845395, 2023).
cancer (continued). "To differentiate prognostic and predictive effects, we assessed the survival of cancer populations expressing defining markers of B cells, CD38 and CD19 using publicly available data (GEPIA2)." (PMID 37365284, 2023). "We have developed a fully human antibody of another antibody class, IgE, targeting the CD38 molecule that is expressed on the surface of several cancers including MM." (PMID 37760502, 2023). "Given the relevance of CD38 as a MM antigen and the attractive properties of the IgE antibody, we developed a fully human anti-CD38 IgE and evaluated its properties, including anti-cancer effects, in vitro and in vivo." (PMID 37760502, 2023). "The ATRA works by increasing the CD38 expression in cancer cells and boosting the complement-dependent and antibody-mediated cytotoxic properties of daratumumab." (PMID 37608887, 2023). "This subset of peripheral CD8+ T cells, expressing conventional activation markers (HLA-DR+CD38+) and proliferation marker (Ki67+), was associated with better response to ICB therapies in a variety of cancer types." (PMID 37881432, 2023). "How anti-CD38 therapy influences normal PCs or PC differentiation beyond depletion in cancer settings has remained virtually unexplored." (PMID 37419630, 2023). "We then identified that all-trans retinoic acid (ATRA) upregulates CD38 expression in CD38low cancer cells and displays synergistic activity with CD38-CAR T cells and daratumumab." (PMID 35765110, 2022). "These complex receptor and enzymatic roles of CD38 have led researchers to implicating it in several diseases primarily related to inflammation, immunomodulation and cancer." (PMID 35712720, 2022). "The potent cancer cell-eliminating ability of CD38-redirected CAR T cells and daratumumab armed with ATRA supports the conclusion of promising therapeutic options for lymphoid malignancies." (PMID 35765110, 2022). "In our current report, we found an increase in CD38 expression in B cells after RT in cancer patients." (PMID 36426217, 2022). "Overexpression of CD38 is often viewed as a malignant phenotype, and the mechanisms of CD38 mab against CD38 + cancer cells are diverse." (PMID 35906622, 2022). "Deeper analysis about co-expression between CD38 and immune checkpoint molecules provides new insight to expand and improve the efficacy of immune checkpoint blockading in cancer treatment." (PMID 35725444, 2022). "The second antigen-binding domain binds another target, e.g., other antigen associated with cancer (CD19, CD38, HER2, EGFR, CEA, or IL-13R-a2), or a cancer-related ligand (IL-13, heregulin, VEGF)." (PMID 33482842, 2021). "Among the 158 paired adjacent and cancer tissue microarrays, we found that 62% of cancer case exhibited positive staining for CD38, while only 28.3% were positive for adjacent tissue (p < 0.001)." (PMID 34226519, 2021). "Preclinical studies showed potent killing of CD38+ cancer cell lines, whereby cell lysis was directly correlated with the level of target expression." (PMID 34640611, 2021). "The correlation between GTSF1L and ICI-related genes such as PD1, PD-L1, CTLA4, and CD38 was computed by Pearson analysis in all types of cancers from the TCGA cohort." (PMID 34539641, 2021). "Our aim was to emphasize the role of CD38 on the immune suppression of some malignant neoplasms and to emphasize its role as an interesting target for cancer immunotherapy." (PMID 33727923, 2021). "Yet, the mapped genes were highly relevant to PCa etiology and included known cancer drivers LDLRAD4, GMNN, COL1A1, CD38, PTPRN2, GTSE1 and CAMK2N1 in the risk signature and KLK2, AR, KLK3, SPDEF in the relapse signature." (PMID 33845808, 2021). "Only CD38 level (that correlated with MyoICA expression in vitro) demonstrated statistically significant differences between cancer and non-cancer specimens." (PMID 34019593, 2021).
cancer (continued). "Through RNAseq database searches, we investigated the magnitude of expression of the genes involved in adenosinergic pathway, namely, CD39 (ENTPD1 gene), CD73 (NT5E gene), and CD38 (also responsible for eADO generation) among female HER2+ cancers." (PMID 34948316, 2021). "Here, we demonstrate that infiltration of Th17 cells and stimulation of cancer cells with IL-17 is a mechanism of CD38 upregulation following treatment to promote immunotherapy resistance." (PMID 33972557, 2021). "AMG424 was selected out of a panel of CD38 x CD3 BsAbs based on its ability to effectively eliminate cancer cells expressing high and low levels of CD38, but with attenuated cytokine release (because of relatively low CD3 binding affinity)." (PMID 34640611, 2021). "Because of what has been mentioned, the efficacy of anti-CD38 antibodies in many other cancers is being evaluated in preclinical and initial stages of clinical trials." (PMID 33727923, 2021). "These CD38+ TILs secrete high levels of IFNγ and in combination with Sorafenib, a kinase inhibitor used for advanced cancer, patients' survival improves notably." (PMID 33727923, 2021). "CD4+ T cell counts and percentages of CD8+ HLA‐DR/CD8+ and CD8+ CD38+/CD8+ can be potential blood biomarkers of cancer progression." (PMID 32459060, 2020). "CD4+ T‐cell counts and percentages of CD8+ HLA‐DR/ CD8+ and CD8+ CD38+/ CD8+ can predict the cancer progression." (PMID 32459060, 2020). "Additional candidate drivers in fBM following maternal OM-85 treatment included CD38, IL5, and an array of microRNAs (miR) recognized principally in the context of cancer-associated functions." (PMID 33424847, 2020). "In agreement with previous reports, we discovered that there were high CD8+ HLA‐DR+/CD8+ and CD8+ CD38+/CD8+ T‐cell percentages in patients with all cancer types compared with controls, suggesting that the immune system was activated during carcinogenesis." (PMID 32459060, 2020). "A recent study using a murine lung cancer model reported that CD38 expression on cancer cells was upregulated in response to PD-1/PD-L1 blockade, resulting in the inhibition of CD8+ T-cell function via adenosine receptor signaling." (PMID 31552039, 2019). "Isatuximab demonstrates potent direct killing activity based on a greater increase in apoptosis of CD38-expressing cancer cells." (PMID 31779273, 2019). "When Bonnet & Dick showed that in Acute Myeloid Leukaemia (AML), this subset of cells had an exclusive phenotype (CD34+/CD38–), a new model to explain cancer cell heterogeneity was proposed: cancer stem cells (CSC)." (PMID 31834886, 2019). "These promising findings suggest that the CD38/CD203a/CD73 adenosinergic pathway represents an effective target for cancer immunotherapy." (PMID 31861847, 2019). "Binding of isatuximab to CD38 on MM cells triggers multiple mechanisms that can lead to the death of the target cancer cells." (PMID 31779273, 2019). "By now, several effective anti-human CD38 mAbs have been generated against several forms of human CD38+ cancers such as MM." (PMID 31118070, 2019). "Emerging data demonstrate that CD38 knockout mice under high metabolic pressure, such as high fat diets, are protected against the development of cancers and have increased longevity." (PMID 31214171, 2019). "It is clear that the dual enzymatic and receptorial functions of CD38 mean that this glycoprotein affects the immune response in a number of ways, and these must be fully characterized to improve the accuracy of cancer prognosis and efficacy of treatment." (PMID 31861847, 2019). "Recent work has described CD38/CD203a as an alternative mechanism of ATP catabolism by both human T cells (perhaps especially Tregs) and cancer cells." (PMID 29942314, 2018). "It will be important to evaluate in detail what these effects are and how monocyte/macrophage CD38 blockade modulates anti-cancer/anti-SLE therapeutic effects." (PMID 30042766, 2018).
cancer (continued). "Repeated injections of the IC maintained high-titre lytic IgG abs against the cancer specific CD38 ag, resulting in cancer cell death/elimination by developing pathogenic IgG autoantibodies (aabs)." (PMID 30577575, 2018). "Cancers with CD38-, ARG2- expression patterns, corresponding to an undifferentiated state, had significantly lower 10-year recurrence-free survival compared to the most differentiated group (CD38+ARG2+)." (PMID 29464091, 2018). "Taken together, these results strongly suggest that Wnt pathway in stem-like cancer cells regulates the expression of both CD38 and ALP, thereby fine-tuning the levels of NAADP and NAAD+ according to the context-dependent cellular needs." (PMID 27391070, 2016). "Collectively, these results clearly demonstrate that OGD induces cell death by activating the CD38/cADPR/RyR/Ca2+/CaMKII/AMPK signaling pathway in NQO1-expressing cancer cells." (PMID 25586669, 2015). "Taken together, we conclude that NQO1 plays a key role in the AMPK-induced cancer cell death in OGD through the CD38/cADPR/RyR/Ca2+/CaMKII signaling pathway." (PMID 25586669, 2015). "The presence of elevated levels of a soluble form of CD38 has also been shown in serum samples from cancer patients." (PMID 23946809, 2013). "Several proteins positively associated with MVPA are inversely associated with disease risk (e.g., integrins, CLEC4A for cancer; LPL, LEP for T2D), while proteins negatively associated with MVPA are positively associated with disease risk (e.g., CD38, TGFA for CVD)." (PMID 41826625, 2026). "Elevated CD38 expression in these cancers has been reported, but the biological significance of this finding remains unclear." (PMID 40529366, 2025). "For both cost functions a high initial drug dose in the full model rapidly reduces overall cancer levels, but produces much higher levels of the drug-immune CD38- population, and recovery of the healthy cell population is inhibited by the off-target effect while the control dose is high." (PMID 40788967, 2025). "At the same time, opposing findings indicate that CD24+CD38+ Bregs from non-sentinel lymph nodes in HNSCC patients are associated with limited cancer infiltration and low histologic grade, both positive prognostic markers." (PMID 40136652, 2025). "Since Snail plays a critical role in inducing EMT by repressing E‐cadherin expression, we reasoned that CD38 might regulate Snail expression to activate cancer cell EMT program." (PMID 38545257, 2024). "Thus, targeting CD38 represents a potential strategy to improve the efficacy of anti-PD1 treatment in cancer." (PMID 38451948, 2024). "Inhibitors targeting CD38, which is already being explored in other inflammatory conditions and cancers, could help reduce immune cell activation and inflammation in UC." (PMID 39596612, 2024). "Consequently, it offers a rationale for targeting CD38 to enhance the therapeutic efficacy of PD1 blockade therapy in cancer." (PMID 38451948, 2024). "Beyond MM, the expression of CD38 in other types of cancer, which is generally more heterogeneous than in MM, suggests that [68Ga]Ga‐AJ206 may have a role in selecting those patients that might benefit from CD38 directed therapies." (PMID 38421139, 2024). "Notably, a significant positive correlation between the expression of CD38 and all of these genes was revealed, suggesting the potential link of cancer cell metabolism reprogramming with CD38 expression." (PMID 38545257, 2024). "However, ADPR produced extracellularly by CD38 through NAD degradation activates TRPM2, which also plays a role in Ca2+ signalling, linked to the survival, proliferation and metabolic status of cancer cells." (PMID 39364393, 2024). "Clinical trials to evaluate drug effects on CD38 inhibition in cancer treatments." (PMID 38116009, 2023).